EBLN2 (endogenous Bornavirus like nucleoprotein 2)
Description:
May act as an RNA-binding protein. The C-terminal region is highly homologous to the bornavirus nucleocapsid N protein that binds viral RNA and oligomerizes. The viral protein also possesses a nuclear import and a nuclear export signal. These 2 signals seem absent in EBLN-2 supporting an unrelated function in Human.
Synonyms: EBLN-2
Tractability: No criterion of Open Targets' tractability assessment is met for any kind of drug.
Gene: Protein-coding gene on chromosome 3 (73,061,659 to 73,063,337, forward strand). Ensembl gene ENSG00000255423.
Subcellular location (Human Protein Atlas): Nuclear bodies; Nucleoplasm
Genetic constraint (gnomAD): Loss-of-function variants: 8 observed, 4.06 expected, observed/expected ratio (o/e) 1.97. That is too few expected variants to judge how well the gene tolerates losing a copy. Missense variants: 369 observed, 311.87 expected, observed/expected ratio (o/e) 1.18, 90% interval 1.09 to 1.29. Synonymous variants: 123 observed, 108.99 expected, observed/expected ratio (o/e) 1.13, 90% interval 0.97 to 1.31.
Homologues: Orthologues: chimpanzee EBLN2 (74% identical). Paralogues in human: EBLN1 (60% identical).